CLDN10 (claudin 10)
Description:
Forms paracellular channels: polymerizes in tight junction strands with cation- and anion-selective channels through the strands, conveying epithelial permeability in a process known as paracellular tight junction permeability. [Isoform 1]: Forms cation-selective paracellular channels. In sweat glands and in the thick ascending limb (TAL) of Henle's loop in kidney, it controls paracellular sodium permeability which is essential for proper sweat production and renal function. [Isoform 2]: Forms anion-selective paracellular channels. In renal proximal tubules, it conveys selective chloride over hydrogencarbonate anion permeability which is required for renal chloride reabsorption and salt homeostasis.
Synonyms: OSP-L; CPETRL3; HELIX; OSPL
Tractability: Antibody: UniProt places it where antibodies can reach, with high confidence; its Gene Ontology location is reachable by antibodies, with high confidence; UniProt predicts a signal peptide or a membrane-spanning region.
Gene: Protein-coding gene on chromosome 13 (95,433,604 to 95,579,759, forward strand). Ensembl gene ENSG00000134873.
Subcellular location: Cell junction, tight junction (Isoform 1); Cell membrane; Cell junction, tight junction (Isoform 2)
Pathways (Reactome):
Cell-Cell communication: Tight junction interactions
Developmental Biology: Developmental Lineage of Pancreatic Ductal Cells
Gene Ontology:
Molecular function: protein binding; identical protein binding; paracellular tight junction channel activity; structural molecule activity
Biological process: regulation of monoatomic ion transport; calcium-independent cell-cell adhesion; cell adhesion; paracellular transport
Cellular component: plasma membrane; bicellular tight junction; cytoplasm; membrane
Genetic constraint (gnomAD): Loss-of-function variants: 12 observed, 16.09 expected, observed/expected ratio (o/e) 0.75, 90% interval 0.48 to 1.21. The upper end of that interval is the gene's LOEUF score, 1.21, which puts it in group 5 of 6, group 1 being the genes least tolerant of losing a copy. Missense variants: 195 observed, 243.77 expected, observed/expected ratio (o/e) 0.8, 90% interval 0.71 to 0.9. Synonymous variants: 97 observed, 97.98 expected, observed/expected ratio (o/e) 0.99, 90% interval 0.84 to 1.17.
Homologues: Orthologues: chimpanzee CLDN10 (100% identical), macaque CLDN10 (99% identical), rabbit CLDN10 (98% identical), pig CLDN10 (97% identical), dog CLDN10 (97% identical), rat Cldn10 (96% identical), mouse Cldn10 (94% identical), guinea pig CLDN10 (75% identical), zebrafish cldn10a (68% identical), zebrafish cldn10b (64% identical), zebrafish cldn10d (39% identical). Paralogues in human: CLDN15 (40% identical), CLDN3 (35% identical), CLDN7 (33% identical), CLDN6 (32% identical), CLDN19 (32% identical), CLDN5 (32% identical), CLDN4 (31% identical), CLDN9 (31% identical), CLDN1 (31% identical), CLDN8 (30% identical), CLDN14 (30% identical), CLDN17 (30% identical), and 10 more.
Diseases named in the same sentence as CLDN10 in open-access papers:
CLDN10 is named in the same sentence as 76 diseases in open-access papers, as found by Europe PMC text mining. Sharing a sentence is not in itself a finding about the gene and the disease. The quoted sentences say what the papers report.
hepatocellular carcinoma (11 papers, 2008 to 2025). A malignant tumor that arises from hepatocytes. "An association between claudin-10 gene expression and disease recurrence in hepatocellular carcinoma was suggested by the finding that patients with high expression of claudin-10 had shorter disease-free survival." (PMID 24009024, 2013). "Expression levels of CLDN10 are associated with recurrence of primary hepatocellular carcinoma." (PMID 18211683, 2008). "Claudin-10 is a member of the Claudin family, which influences the progression of thyroid cancer, lung adenocarcinoma, hepatocellular carcinoma, breast cancer, ependymomas, and esophageal squamous cell carcinomas." (PMID 40242686, 2025). "Previous studies reported that CLDN10 (claudin-10), as a member of the claudins family, played a vital role in different tumors, including hepatocellular carcinoma 14, papillary thyroid cancer 15, and gastric cancer." (PMID 35414767, 2022). "Multivariate analysis confirmed that claudin-10 gene expression is an independent predictor in recurrence of hepatocellular carcinoma." (PMID 24009024, 2013). "For example, claudin-3 and claudin-4 were expressed at high levels in endometrioid adenocarcinoma and prostate cancer; claudin-10 expression was up-regulated in hepatocellular carcinoma and thyroid papilloma; claudin-2 has been reported to be up-regulated in thyroid cancer and endometrial cancer." (PMID 24245968, 2013). "Similarly, in hepatocellular carcinoma cells, claudin-10 expression promoted cell survival, motility, and invasiveness, while matrix metalloproteinase 2 (MMP2) was up-regulated." (PMID 21789222, 2011). "CLDN10 is upregulated in hepatocellular carcinoma (HCC) tissues, and patients with higher CLDN10 protein level prone to develop a poor prognosis." (PMID 34187591, 2021). "miR-486 targets Pim-1 kinase in lung cancer, OLFM4 in gastric cancer, CLDN10 and CITRON in hepatocellular carcinoma, and plasminogen activator inhibitor-1 in human myxoid liposarcoma." (PMID 26871282, 2016). "For claudin 10 (CLDN10), most of the literature to date shows an involvement in cancer progression, especially of hepatocellular carcinoma." (PMID 23284715, 2012). "Similarly, in hepatocellular carcinoma (HCC) cells, claudin-10 was detected in the cytoplasm." (PMID 36428908, 2022).
papillary thyroid carcinoma (10 papers, 2020 to 2024). "This study demonstrated that abnormal CLDN10 expression was associated with lymph node metastasis in papillary thyroid carcinoma, yet patients have a better prognosis." (PMID 34721537, 2021). "This includes claudin-2 in oral squamous cell cancer, claudin-3 in ovarian and laryngeal cancers, and claudin-10 in papillary thyroid cancer." (PMID 38540693, 2024). "CLDN10 overexpression promotes carcinogenesis in papillary thyroid cancer, which has a poor prognosis." (PMID 35281827, 2022). "CLDN10 also promotes papillary thyroid cancer cell growth and invasion, similarly, patients in high-expressed CLDN10 group show a worse prognosis." (PMID 34187591, 2021). "Previous reports have shown that CLDN10 is highly expressed in hepatocellular carcinoma, papillary thyroid carcinoma and lung adenocarcinoma." (PMID 34721537, 2021). "Further analysis found a positive correlation between levels of immune-infiltrating cells in thyroid papillary carcinoma with high expression of CLDN10, thus explaining the improved prognosis." (PMID 34721537, 2021). "However, infiltration of B cells, CD8 + T cells, and macrophages as a consequence of increased CLDN10 expression improves the prognosis of patients with papillary thyroid carcinoma." (PMID 35281827, 2022). "Studies have shown that CLDN10 is highly expressed in thyroid papillary carcinoma, and can affect cell proliferation, migration, and invasion in vitro; further, it plays the role of a tumor promoter, and the up-regulation of CLDN10 is related to lymph node metastasis." (PMID 34631779, 2021). "CLDN10, a glandular epithelial marker in epithelial ovarian cancer, was reported to be a key immune-related gene in clear cell renal cell carcinoma and papillary thyroid carcinoma." (PMID 34249076, 2021). "A higher expression of claudin-10 was also observed in several carcinomas, such as HCC, papillary thyroid cancer, and biliary tract cancers, and was correlated with a shorter overall survival in HCC." (PMID 36428908, 2022). "Claudin-10 (CLDN10) has been reported to be upregulated in papillary thyroid cancer and KRAS mutant non-squamous cell lung cancer and reduced in clear cell renal cell carcinoma." (PMID 38540693, 2024).
HELIX syndrome (9 papers, 2020 to 2025). "CLDN10 is associated with HELIX syndrome (#617671), as biallelic mutations cause dysfunction in tight junctions in several tissues, and subsequent abnormalities in renal ion transport, ectodermal gland homeostasis, and epidermal integrity." (PMID 37980427, 2023). "The molecular cause for CLDN16 dominance remains unexplained, but it is also reflected in the widespread expression of CLDN16 at all cell borders when CLDN10 is deleted in mice and in human HELIX syndrome, in which mutations in CLDN10 lead to hypermagnesemia and nephrocalcinosis." (PMID 40471686, 2025). "CLDN10 mutation in humans causes Helix syndrome, which shows enamel wear as phenotype." (PMID 32984333, 2020). "Mutations in CLDN10 of humans are associated with HELIX syndrome and cause enamel defects." (PMID 33195274, 2020). "HELIX syndrome (Hypohidrosis-Electrolyte disturbances-hypoLacrimia-Ichthyosis-Xerostomia) (MIM#617671) (ORPHA:528105), described in 2017, is due to an abnormal claudin 10 b protein, secondary to pathogenic CLDN10 variants." (PMID 38927623, 2024). "This suggests that the CLDN10 mutation, responsible for the HELIX syndrome, does not alter enamel formation." (PMID 35902997, 2022). "In addition, patients with HELIX syndrome show enamel defects, indicating that Cldn10 may play a role in enamel formation." (PMID 33195274, 2020). "Whereas claudin-10b fs(SA) neither interacted with claudin-10 wt nor affected its localization, claudin-10b fs interfered with claudin-10 wt localization, likely explaining a mild dominant effect that is distinct from the molecular phenotype of the HELIX syndrome causing mutation." (PMID 36890159, 2023).
ovarian carcinoma (8 papers, 2020 to 2025). A malignant neoplasm originating from the surface ovarian epithelium. "Claudin 10 (CLDN10) has been found to be associated with ovarian cancer progression via TGF-beta or WNT/Beta-catenin induced epithelial to mesenchymal transition." (PMID 36699376, 2022). "It has been reported that Claudin-10’s decreased expression can be used as a predictor, showing a lower overall survival rate in patients with ovarian cancer, and its increased expression is associated with better relapse-free survival in patients with breast cancer." (PMID 40242686, 2025). "TGFβ or WNT/β-catenin-induced epithelial-mesenchymal transition (EMT) and tumor resistance may be linked to CLDN10, which offers promise as a prognostic biomarker in ovarian cancer." (PMID 35281827, 2022). "In ovarian cancer, a low expression level of CLDN10 is associated with a less favorable prognosis." (PMID 34187591, 2021). "The expression levels of CLDN6 and CLDN10 were also negatively correlated and positively correlated, respectively, with various gene markers of immune cells in ovarian cancer." (PMID 34249076, 2021). "Our study showed that CLDN6 and CLDN10 were prognostic biomarkers correlated with the immune microenvironment in ovarian cancer." (PMID 34249076, 2021). "This study revealed that the prognostic potential of CLDN6 and CLDN10 is related to the tumor immune microenvironment in ovarian cancer." (PMID 34249076, 2021). "Our results revealed new roles for CLDN6 and CLDN10 in ovarian cancer and their potential as therapeutic targets in cancer treatment." (PMID 34249076, 2021). "In contrast, CLDN10 expression was positively correlated with gene markers of dendritic cells, T cells (general), and TAMs in ovarian cancer." (PMID 34249076, 2021). "CLDN6 and CLDN10 were identified as potential prognostic biomarkers and were correlated with immune cell infiltration in ovarian cancer." (PMID 34249076, 2021). "Consistent with previous reports, both CLDN6 and CLDN10 showed high expression in ovarian cancer." (PMID 34249076, 2021). "Furthermore, CLDN6 and CLDN10 were negatively correlated and positively correlated, respectively, with immune cell infiltration in ovarian cancer." (PMID 34249076, 2021). "Furthermore, CLDN10 expression has proved to be a prognostic marker for ovarian cancer." (PMID 34249076, 2021). "Thus, CLDN6 and CLDN10 may participate in immune cell infiltration in ovarian cancer, and these mechanisms may be the reason for poor prognosis." (PMID 34249076, 2021). "Among them, CLDN3, CLDN4, CLDN6, CLDN10, CLDN15, and CLDN16 were significantly correlated with overall survival in patients with ovarian cancer." (PMID 34249076, 2021). "Eight genes were overexpressed in ovarian cancer samples compared with normal tissue samples and included CLDN1, CLDN3, CLDN4, CLDN6, CLDN7, CLDN9, CLDN10, and CLDN16." (PMID 34249076, 2021). "In addition, high expression of CLDN10 and CLDN15 were predictive of a good prognosis in ovarian cancer patients." (PMID 34249076, 2021). "However, claudin-1, claudin-4, and claudin-10 have been shown to be differentially expressed during the EMT in oral lichen planus and ovarian carcinomas." (PMID 33193109, 2020).
gastric cancer (6 papers, 2013 to 2024). A primary or metastatic malignant neoplasm involving the stomach. "Currently, there is a lack of systematic studies to identify the underlying value of CLDN10 in the prognosis and clinicopathological characteristics of gastric cancer." (PMID 34721537, 2021). "Down-regulated CLDN10 was associated with better overall survival (OS) in gastric cancer." (PMID 34721537, 2021). "In summary, CLDN10 is down-regulated in gastric cancer and associated with a better prognosis." (PMID 34721537, 2021). "In terms of treatment, the expression of CLDN10 in gastric cancer patients who have only undergone surgery was related to OS and PFS (OS p = 0.017; PFS p = 0.044)." (PMID 34721537, 2021). "A statistically significant correlation between CLDN10 expression and gastric cancer prognosis was observed in stage N0\N1\N3\N1+2 + 3 patients but not N2." (PMID 34721537, 2021). "High CLDN10 expression was associated with poor OS and PFS in both male and female gastric cancer patients (p < 0.05)." (PMID 34721537, 2021). "Next, we evaluated the relationship between CLDN10 expression level and prognosis of gastric cancer." (PMID 34721537, 2021). "It was seen that low CLDN10 expression was associated with better OS, PFS, and DFS in gastric cancer patients." (PMID 34721537, 2021). "Correlations between CLDN10 expression and clinical outcomes of gastric cancer were explored by Kaplan-Meier Plotter." (PMID 34721537, 2021). "In this study, Oncomine, UALCAN, HPA and TIMER2.0 databases were used to evaluate the expression levels of CLDN10 mRNA and protein in gastric cancer." (PMID 34721537, 2021). "To more accurately assess CLDN10 mRNA expression in gastric cancer, we used the Oncomine and UALCAN database to verify CLDN10 expression levels." (PMID 34721537, 2021). "Here Oncomine, ULCAN, Human Protein Atlas (HPA), Kaplan–Meier plotter and GEPIA 2.0 were used to analyze CLDN10 expression and its correlation with the prognosis and clinicopathological features of gastric cancer." (PMID 34721537, 2021). "The regulatory mechanism of differential expression of CLDN10 and prognosis of gastric cancer needs to be further verified by well-designed studies." (PMID 34721537, 2021). "The results from these four databases mutually confirmed that the expression level of CLDN10 in gastric cancer tissues was lower than that in adjacent normal tissues." (PMID 34721537, 2021). "In order to better understand potential correlations of CLDN10 expression in gastric cancer, we used Kaplan-Meier Plotter and GEPIA2.0 database to investigate the prognosis and clinicopathological significance of CLDN10." (PMID 34721537, 2021). "More interestingly, according to the information provided by HPA, CLDN10 protein was located in cytoplasm and cell membrane in both gastric cancer and normal tissues." (PMID 34721537, 2021). "And CLDN10 was also down-regulated in gastric cancer cell lines when compared with human gastric mucosa cell line." (PMID 34721537, 2021). "further experiments are needed to verify the mechanism of CLDN10 regulating immune infiltration in the gastric cancer tumor microenvironment; iii." (PMID 34721537, 2021). "Our data revealed an important role of CLDN10 in gastric cancer, and to some extent explains the potential relationship and mechanism of the interaction between CLDN10 and the immune system." (PMID 34721537, 2021). "To determine the differential expression of CLDN10 in both gastric cancers and various other cancer types, we used the TIMER 2.0 database to investigate the CLDN10 mRNA expression in human cancers." (PMID 34721537, 2021). "The results show variable and heterogenous expression of claudin-10, -14 and-17 in gastric carcinoma." (PMID 24325792, 2013). "Positive expression of claudin-10 protein was found in 24.0% (12/50) of gastric carcinoma tissues and in 72% (36/50) of adjacent tissues." (PMID 24325792, 2013).